OGA (O-GlcNAcase)
Diseases named in the same sentence as OGA in open-access papers (continued):
Sharing a sentence is not in itself a finding about the gene and the disease.
neuroblastoma (5 papers, 2014 to 2024). Neuroblastoma (NB) is the most common solid, extracranial childhood tumor. "We used patient-derived induced pluripotent stem cells, a transgenic mouse model of AD, SH-SY5Y neuroblastoma cell lines to examine the effect of sustained O-GlcNAcase inhibition by Thiamet-G (TMG) or OGT deficiency on mitophagy using biochemical analyses." (PMID 39175808, 2024). "In our current study, we show that OGA inhibition increases mitophagy in SH-SY5Y neuroblastoma cells, C57BL6J mice brains, and organoids differentiated from normal individuals." (PMID 39175808, 2024). "Overexpression of either OGT or OGA in SH-SY5Y neuroblastoma cells lowers mitochondrial respiration, disrupts morphology, and decreases the expression of respiratory chain and tricarboxylic acid cycle (TCA) proteins." (PMID 38192280, 2023). "Previously, Ingenuity pathway analysis of RNA Sequencing data from long-term OGA inhibition by Thiamet-G (TMG) in SH-SY5Y neuroblastoma cells predicted that ERK signaling is significantly up-regulated." (PMID 37469955, 2023). "We used patient-derived induced pluripotent stem cells, a transgenic mouse model of AD, SH-SY5Y neuroblastoma and HeLa cell-lines to examine the effect of sustained O-GlcNAcase inhibition by Thiamet-G (TMG) on ISRmt using biochemical analyses." (PMID 38192280, 2023). "More relevant for NDDs, knockout of OGA in C. elegans and OGA inhibitors used in neuroblastoma SH-SY5Y cells, N2a cells, primary rat neurons and within the brains of different mouse models, all induced autophagy using a wide range of autophagy assays and markers." (PMID 37918804, 2023). "Interestingly, ERK signaling was predicted to be significantly upregulated via Ingenuity Pathway Analysis (IPA) of RNA sequencing data in SH-SY5Y neuroblastoma cells after increased O-GlcNAcylation from long-term treatment with O-GlcNAcase (OGA) inhibitor Thiamet-G (TMG)." (PMID 37469955, 2023). "In our current study, we show that disruptions to O-GlcNAc homeostasis by OGA inhibition, OGA KD, and OGT knock-down (KD) all increase ERK phosphorylation in SH-SY5Y neuroblastoma cells." (PMID 37469955, 2023). "We did a serum reactivation time-course followed by western blot in SH-SY5Y neuroblastoma cells after long-term O-GlcNAcase (OGA) inhibition by Thiamet-G (TMG) treatment, O-GlcNAc transferase (OGT) knock-down (KD) and OGA KD." (PMID 37469955, 2023). "We altered the O-GlcNAc levels of SH-SY5Y neuroblastoma, HeLa cervical carcinoma, and K562 leukemia cells with TMG and measured O-GlcNAc, OGT, and OGA levels at various time points up to 48 h of TMG treatment." (PMID 25520704, 2014).
cholangiocarcinoma (4 papers, 2014 to 2023). A carcinoma that arises from the intrahepatic biliary tree (intrahepatic cholangiocarcinoma) or from the junction, or adjacent to the junction, of the right and left hepatic ducts (hilar cholangiocarcinoma). "Higher O-GlcNAcylation and OGT levels, and lower OGA levels, were observed in cholangiocarcinoma compared with those in normal bile ducts, and this change led to poor prognosis of patients with cholangiocarcinoma." (PMID 36104770, 2022). "Researchers have employed immunohistochemistry to demonstrate that in cholangiocarcinoma tissue samples, both OGT and overall O‐GlcNAcylation levels exhibit significant elevation, while OGA levels are concurrently found to be reduced." (PMID 38116061, 2023).
dilated cardiomyopathy (4 papers, 2022 to 2025). Cardiomyopathy which is characterized by dilation and contractile dysfunction of the left and right ventricles. "In the heart, PRMT5 regulates the RNA splicing of the O-GlcNAcase (Oga) gene, and its dysfunction results in elevated levels of protein O-GlcNAcylation, contributing to the development of dilated cardiomyopathy." (PMID 40076920, 2025). "Changes in the maturation of OGA mRNA are also detected in human dilated cardiomyopathy, demonstrating the importance of maintaining OGA expression for normal cardiac function." (PMID 36359905, 2022). "Interestingly the overexpression of cardiac OGT in transgenic mice also showed to have adverse effects leading to sever dilated cardiomyopathy by increasing O-GlcNAc levels, effects that were counteracted with an overexpression of OGA." (PMID 38737268, 2024).
leukemia (4 papers, 2014 to 2024). A malignant (clonal) hematologic disorder, involving hematopoietic stem cells and characterized by the presence of primitive or atypical myeloid or lymphoid cells in the bone marrow and the blood. "To test this hypothesis, we examined the effects of the OGA inhibitor MK8719 on the growth capacity of leukemia cells impacted by TRAF6 loss." (PMID 38609495, 2024). "Given that a broad range of metabolic enzymes are targets of O-GlcNAcylation, the metabolic status in leukemia cells is likely finely regulated by the balance between OGT and OGA expression and activity." (PMID 38609495, 2024). "In various cancer cell lines, the expression levels of OGT and OGA rank first and second in myeloma and leukemia, respectively; in tumor samples from the TCGA database, the expression of OGT and OGA in LAML was much higher than that in other cancers." (PMID 36104770, 2022).
lung carcinoma (4 papers, 2017 to 2023). "SMAD4 protein levels were checked by treating A549 lung cancer cells with inhibitors of O-GlcNAc editing enzymes which caused thiamet-G, an OGA inhibitor, to increase SMAD4 levels whereas SMAD4 levels decreased when treated with OSMI-1, an OGT inhibitor." (PMID 33199824, 2020). "To investigate the existence of feedback loops for the maintenance of cellular O-GlcNAc homeostasis in lung cancer cells, we examined the expression of OGA and OGT under conditions with varying extents of cellular O-GlcNAcylation." (PMID 33801653, 2021). "In this study, we investigated the O-GlcNAc-feedback regulation of OGT and OGA expression in lung cancer cells." (PMID 33801653, 2021). "Here, we found that hyper-O-GlcNAcylation in lung carcinoma cells by O-GlcNAcase inhibition renders the cells to apoptosis resistance to cisplatin (CDDP)." (PMID 28878262, 2017). "More recently, the involvement of OGA in lung cancer has been investigated." (PMID 37880766, 2023). "We suggest that OGT is regulated through the control of translational efficiency by 4E-BP1, while the expression of OGA could involve epigenetic mechanisms in transcriptional control in lung cancer cells." (PMID 33801653, 2021). "It remains to be determined whether this control mechanism of OGT and OGA expression is also employed by lung cancer cells." (PMID 33801653, 2021). "We set out to determine at which level of gene expression that regulation of OGA might occur in lung cancer cells in response to changes of O-GlcNAcylation status." (PMID 33801653, 2021). "Additionally, we analyzed the mRNA expression of OGT and MGEA5 (encoded OGA) using OncomineTM bioinformatics database and found a remarkable increase in the OGT and/or a decrease in the MGEA5 in lung carcinoma tissues compared with normal lung tissues in many datasets." (PMID 28878262, 2017). "In this study, we have demonstrated that the regulatory mechanisms associated with modulating levels of O-GlcNAc-cycling enzymes according to cellular O-GlcNAcylation status appear to be different for OGA and OGT in lung cancer cells." (PMID 33801653, 2021). "To investigate the role of O-GlcNAcylation in the apoptosis response of lung carcinoma to CDDP, we used small molecule inhibitors of OGA and CRISPR-mediated repression of MGEA5 to elevate the level of global O-GlcNAcylation." (PMID 28878262, 2017).
Obesity (4 papers, 2018 to 2023). Accumulation of substantial excess body fat. "Future investigations into the source of this shift - whether differences in O-GlcNAc levels, OGT/OGA targeting, or the larger O-GlcNAc interactome – may prove fruitful in delineating and abrogating the self-sustaining pathways between progressive obesity and metabolic disease." (PMID 36111295, 2022). "In obesity models, OGT and/or OGA protein were not always altered but when they were, it was generally consistent with the change in protein O-GlcNAcylation." (PMID 36111295, 2022).
ovarian carcinoma (4 papers, 2022). A malignant neoplasm originating from the surface ovarian epithelium. "Finally, we found aberrant expression of OGT and OGA to be associated with ovarian cancer patient survival." (PMID 35795059, 2022). "More importantly, we found the aberrant expression of OGT was significantly correlated with the pathological stage in ovarian cancer patients, while changes in OGA seems only have limited impact." (PMID 35795059, 2022). "In conclusion, our study demonstrates that increased O‐GlcNAc impairs the LPA‐induced migration of OVCAR‐3 cells, suggesting that a reduction in O‐GlcNAc levels and increased OGA expression might facilitate the migration of ovarian cancer cells." (PMID 35347892, 2022). "Collectively, these results indicated that OGT and OGA could substantially influence the survival rate of ovarian cancer patients from several aspects." (PMID 35795059, 2022). "We further show that miR-542-5p might target OGT and OGA, suggesting miR-542-5p as a novel target for ovarian cancer therapy." (PMID 35795059, 2022). "KEGG pathway analysis of OGT/OGA related pathways with ovarian cancer." (PMID 35795059, 2022). "Here, we found that ATM inhibition could elevate the expression of OGT and OGA while significantly suppressing the level of miR-542-5p in ovarian cancer SKOV3 cells When miR-542-5p was overexpressed under ATM inhibition, OGT expression was effectively inhibited." (PMID 35795059, 2022). "Here, we report that administration of the ATM inhibitor KU60019 led to impaired migration and enhanced apoptosis in the ovarian cancer cell line SKOV3, accompanied by abnormally elevated O-GlcNAc transferase and O-GlcNAcase expression levels." (PMID 35795059, 2022). "Our results showed that high expression of OGT/OGA significantly impaired the PFS and PPS in ovarian cancer patients." (PMID 35795059, 2022). "Since significant alteration of OGT and OGA was observed in SKOV3 cells after KU60019 treatment, we next evaluated the prognostic value of these genes in ovarian cancer patients, including overall survival (OS), progression-free survival (PFS), and post-progression survival (PPS)." (PMID 35795059, 2022). "In addition, increased OGA and OGT levels impaired PFS, and shortened PPS in ovarian cancer patients." (PMID 35795059, 2022). "To investigate the impact of OGT/OGA in ovarian cancer patients, we analyzed copy-number alterations of which from the cBioPortal for Cancer Genomics database and found that more up-regulation of OGT could be observed but not OGA." (PMID 35795059, 2022).
heart failure (3 papers, 2020 to 2024). Inability of the heart to pump blood at an adequate rate to meet tissue metabolic requirements. "OGA activity is strongly associated with heart failure, and decreased O-GlcNAcylation is beneficial for combating pressure-overload-induced pathological remodeling and heart failure." (PMID 38790676, 2024). "Pharmacological inhibition of OGA decreased cardiac contractility in heart failure after myocardial infarction, demonstrating the possible role of O-GlcNAcylation in the development of chronic heart dysfunction." (PMID 38790676, 2024). "Here and previously, we found that downregulation of OGA expression occurs following infarct-induced heart failure in mice." (PMID 33253217, 2020). "Conversely, suppression of OGA (and, by extension, increasing O-GlcNAcylation) might attenuate heart failure." (PMID 33253217, 2020). "While OGT and OGA activity have not been examined during heart failure, in models such as IPC and rIPC, elevated O-GlcNAcylation (50%) is associated with increased OGT abundance (100%) and activity (100–300%)." (PMID 37949223, 2023). "Conversely, OGA expression in human heart failure samples is also elevated, not suppressed, as we see in our chronic mouse model." (PMID 33253217, 2020).
ischemia (3 papers, 2015 to 2024). A hypoperfusion of the BLOOD through an organ or tissue caused by a PATHOLOGIC CONSTRICTION or obstruction of its BLOOD VESSELS, or an absence of BLOOD CIRCULATION. "Because there was no concurrent elevation of OGT or decrease of OGA, this dynamic increase in O-GlcNAcylation might be caused by an acute stress response of the brain to severe ischemia." (PMID 26412745, 2015). "To begin to understand the mechanisms regulating O-GlcNAc cycling, we examined the abundance of the O-GlcNAc-cycling enzymes (OGT, OGA, and GFAT2), OGT and OGA activity, and UDP-GlcNAc levels in hearts, either after 20 min of ischemia or after 120 min of reperfusion." (PMID 37949223, 2023).
meningioma (3 papers, 2011 to 2014). A generally slow growing tumor attached to the dura mater. "The OGA gene was found to be identical to MGEA5 a putative hyaluronidase associated with meningioma." (PMID 25386167, 2014). "Human OGA (hOGA) is a 92 kDa multi-domain protein, originally identified as an antigen expressed by meningiomas (MGEA5)." (PMID 24088714, 2013). "The cloned sequence of OGA was found to be identical to the meningioma expressed antigen 5 (MGEA5) gene, previously identified in human meningiomas and described as a hyaluronidase." (PMID 23554695, 2011).
Parkinson disease (3 papers, 2014 to 2024). A progressive degenerative disorder of the central nervous system characterized by loss of dopamine producing neurons in the substantia nigra and the presence of Lewy bodies in the substantia nigra and locus coeruleus. "Pratt and Vocadlo describe the development of potent and highly specific inhibitors of O-GlcNAcase (OGA), and their potential uses as drugs to treat Alzheimer’s and Parkinson’s disease." (PMID 39111732, 2024).
prostate carcinoma (3 papers, 2020 to 2023). A carcinoma that arises from epithelial cells of the prostate gland. "A study using cDNA microarray analysis also showed that the gene encoding OGA is markedly down-regulated by silencing of OGT expression in prostate cancer cell lines." (PMID 33801653, 2021). "In addition, cBioPortal analysis of a clinical data set showed that OGA mRNA levels inversely correlated with HSD3B1 mRNA levels in prostate cancer tissues." (PMID 37009898, 2023).
amyotrophic lateral sclerosis (2 papers, 2021 to 2025). Amyotrophic lateral sclerosis (ALS) is a neurodegenerative disease characterized by progressive muscular paralysis reflecting degeneration of motor neurons in the primary motor cortex, corticospinal tracts, brainstem and spinal cord. "Additionally, a decline in O-GlcNAcylated proteins occurs in spinal cords of mouse models of Amyotrophic Lateral Sclerosis (ALS) during motor neuron atrophy and in mice deficient in a reactive oxygen species (ROS) sensor (NPGPx), a direct modulator of O-GlcNAcase." (PMID 34685706, 2021).
Arthritis (2 papers, 2022 to 2025). Inflammation of a joint. "Thiamet-G, another O-GlcNAcase inhibitor, has been shown to increase O-GlcNAc-modified proteins and reduce the production of pro-inflammatory cytokines (IL-6 and IL-8) in arthritis." (PMID 41300284, 2025). "Potential effects on osteoblasts are thus insufficient to explain the findings obtained with OGT and OGA modulation in our arthritis models." (PMID 35879285, 2022). "Targeted pharmaceutical or genetic inhibition of O-GlcNAc transferase (OGT) or O-GlcNAcase (OGA) arrests osteoclast differentiation during early stages of differentiation and during later maturation, respectively, and ameliorates bone loss in experimental arthritis." (PMID 35879285, 2022).
Cerebral ischemia (2 papers, 2015 to 2021). Restriction of arterial blood supply to the brain associated with insufficient oxygenation to support the metabolic requirements of the tissue. "Therefore, therapeutic strategies that directly or indirectly elevate O-GlcNAc levels through HBP-associated O-GlcNAc signaling are being developed in experimental models of myocardial or cerebral ischemia, such as specific OGA inhibitor thiamet-G or glucosamine." (PMID 34641427, 2021).
developmental delay (2 papers, 2020 to 2021). "Previous studies have revealed that mice deficient in OGA protein (OgaKO) showed developmental delay and die perinatally." (PMID 33610549, 2021). "Furthermore, knocking down OGA in mouse brain leads to microcephaly, hypotonia, and developmental delay, suggesting a possible link between OGT-XLID variants and perturbations of OGA levels." (PMID 32080367, 2020).
glioma (2 papers, 2014 to 2023). A benign or malignant brain and spinal cord tumor that arises from glial cells (astrocytes, oligodendrocytes, ependymal cells). "This suggests that OGT and possibly OGA through O-GlcNAcylation may mediate glioma progression through transcriptional regulation of these genes." (PMID 37689115, 2023).
Glucose intolerance (2 papers, 2022 to 2023). Glucose intolerance (GI) can be defined as dysglycemia that comprises both prediabetes and diabetes. "Under metabolic stress (HFD), OGA deletion led to improved GTT and normal insulin secretion in male mice, and glucose intolerance in females despite improved insulin secretion in vivo." (PMID 36387851, 2022).
mantle cell lymphoma (2 papers, 2020 to 2021). Mantle cell lymphoma is a rare form of malignant non-Hodgkin lymphoma affecting B lymphocytes in the lymph nodes in a region called the ``mantle zone''. "Likewise, hyper-O-GlcNAcylation induced by OGA inhibition was found to sensitize bortezomib-induced apoptosis and reverse bortezomib resistance in mantle cell lymphoma (MCL), suggesting the potential utility of OGA inhibitors such as ketoconazole in adjuvant therapy of MCL." (PMID 33726758, 2021).
myocardial infarction (2 papers, 2011 to 2021). Gross necrosis of the myocardium, as a result of interruption of the blood supply to the area, as in coronary thrombosis. "In a mouse model of myocardial infarction, increased O‐GlcNAc levels with reduced OGA correlated to miR‐539 expression." (PMID 34337900, 2021). "For example, increasing O-GlcNAc levels in cardiac myocytes by treatment with GlcN, PUGNAc or NAG-Bt and NAG-Ae, highly selective O-GlcNAcase inhibitors, protects against ischemia-reperfusion injury and ischemic injury related to myocardial infarction." (PMID 21904602, 2011).
osteosarcoma (2 papers, 2022 to 2024). A usually aggressive malignant bone-forming mesenchymal neoplasm, predominantly affecting adolescents and young adults. "Recently, a clinical study examined O-GlcNAcylation, OGT, and OGA expression in bone specimens derived from 109 patients diagnosed with osteosarcoma." (PMID 38915778, 2024). "Further multivariate analysis indicated that OGA expression was an independent predictor of good prognosis for osteosarcoma." (PMID 38915778, 2024).
pancreatic cancer (2 papers, 2014 to 2024). "In this work, by using the lysates of PANC-1 cells (a pancreatic cancer cell line), we provided a head-to-head comparison of three affinity enrichment methods and materials (i.e., antibody, lectin AANL6, and an OGA mutant) for site-specific O-GlcNAc proteomics." (PMID 39302247, 2024). "Several pancreatic cancer cell lines have increased O-GlcNAc levels when compared to an immortalized control cell line; importantly, OGT protein expression was increased while OGA protein expression was decreased." (PMID 25520704, 2014).